TCEA3 (transcription elongation factor A3)
Description:
Necessary for efficient RNA polymerase II transcription elongation past template-encoded arresting sites. The arresting sites in DNA have the property of trapping a certain fraction of elongating RNA polymerases that pass through, resulting in locked ternary complexes. Cleavage of the nascent transcript by S-II allows the resumption of elongation from the new 3'-terminus.
Synonyms: TFIIS.H; TFIIS
Tractability: PROTAC: ubiquitination databases record sites on it; its protein half-life has been measured.
Gene: Protein-coding gene on chromosome 1 (23,370,591 to 23,425,169, reverse strand). Ensembl gene ENSG00000204219.
Subcellular location: Nucleus
Subcellular location (Human Protein Atlas): Nucleoplasm; Vesicles
Gene Ontology:
Molecular function: protein binding; transcription elongation factor activity; nucleic acid binding; zinc ion binding
Biological process: transcription elongation by RNA polymerase II; DNA-templated transcription
Cellular component: nucleus
Genetic constraint (gnomAD): Loss-of-function variants: 34 observed, 42.58 expected, observed/expected ratio (o/e) 0.8, 90% interval 0.61 to 1.06. The upper end of that interval is the gene's LOEUF score, 1.06, which puts it in group 4 of 6, group 1 being the genes least tolerant of losing a copy. Missense variants: 390 observed, 446.85 expected, observed/expected ratio (o/e) 0.87, 90% interval 0.8 to 0.95. Synonymous variants: 161 observed, 159.6 expected, observed/expected ratio (o/e) 1.01, 90% interval 0.89 to 1.15.
Homologues: Orthologues: chimpanzee TCEA3 (100% identical), macaque TCEA3 (98% identical), pig TCEA3 (93% identical), mouse Tcea3 (91% identical), rat Tcea3 (90% identical), zebrafish tcea3 (65% identical). Paralogues in human: TCEA1 (51% identical), TCEA2 (49% identical), TCEANC (29% identical).
Diseases named in the same sentence as TCEA3 in open-access papers:
TCEA3 is named in the same sentence as 26 diseases in open-access papers, as found by Europe PMC text mining. Sharing a sentence is not in itself a finding about the gene and the disease. The quoted sentences say what the papers report.
ovarian carcinoma (7 papers, 2016 to 2025). A malignant neoplasm originating from the surface ovarian epithelium. "Expression of TCEA3 was lower in cell lines of ovarian carcinoma in which its interaction with receptor TGFβ I induced cell death." (PMID 33670246, 2021). "Recent studies have shown that TCEA3 expression is low in ovarian cancer cell lines compared to normal ovarian epithelial cells and ectopic expression of TCEA3 in ovarian cancer cell lines induces the caspase-dependent mitochondrial cell death pathway." (PMID 31988307, 2020). "In ovarian cancer cell lines, TCEA3 has been shown to induce Smad-independent, JNK-dependent apoptosis." (PMID 31988307, 2020). "Earlier studies claimed that TCEA3 could serve as a potent tumor suppressor, given that it contributed to apoptosis in rhabdomyosarcoma, gastric cancer, and ovarian cancer via multiple signaling pathways (24-, 26)." (PMID 39907426, 2025). "Low expression of tumor suppressor TCEA3 is liable for pathogenesis of ovarian cancer, but decreased expression of this gene may be identified with the growth of GBM." (PMID 31137733, 2019). "As a member of the transcription elongation factor TFIIS family in vertebrates, TCEA3 was significantly downregulated in cancer tissues compared with paired normal tissues; its upregulation could induce apoptosis in gastric cancer, ovarian cancer and rhabdomyosarcoma cell lines 49-51." (PMID 34475994, 2021). "In ovarian cancer cells, the interaction between TCEA3 and TGFβ receptor-I is activated through the Smad-dependent JNK pathway, which induces the death of ovarian cancer cells." (PMID 34354750, 2021).
gastric cancer (6 papers, 2016 to 2025). A primary or metastatic malignant neoplasm involving the stomach. "TCEA3 has also been associated with stomach cancer, in which high expression has been associated with better prognosis, lower proliferation of carcinoma cells and induction of apoptosis." (PMID 33670246, 2021). "In gastric cancer cell lines, TCEA3 is downregulated with respect to normal tissue and exogenous expression promotes apoptosis." (PMID 31988307, 2020). "Functionally, upregulation of TCEA3 inhibits gastric cancer cell proliferation and colony formation, which may attenuate cell growth through apoptosis induction." (PMID 32411183, 2020). "TCEA3 expression is significantly downregulated in gastric cancer tissues." (PMID 32411183, 2020). "Our results are therefore consistent with previous findings on stomach cancer and CRC, thus contributing to understanding the involvement of TCEA3 in CRC cancerogenesis." (PMID 33670246, 2021). "Our results showing that TCEA3 promoted apoptosis in both ERMS and ARMS cell lines were surprising, but supported by studies in both ovarian and gastric cancer." (PMID 31988307, 2020).
breast carcinoma (3 papers, 2013 to 2021). "It has also been shown that knockdown of TCEA3 inhibited the proliferation of breast cancer cells and induces apoptosis, indicating that the protein is required for the survival of cells." (PMID 34630087, 2021). "To test this hypothesis, we examined the expression of TCEA3 in HeLa, PC3, MCF7, and MDA-321 cell lines representing cervical, prostate and breast cancer, respectively." (PMID 31988307, 2020).
colorectal cancer (3 papers, 2021 to 2025). A primary or metastatic malignant neoplasm that affects the colon or rectum. "In this previous study, TCEA3 was found to attenuate pyroptosis and apoptosis of colorectal cancer cells induced by chemotherapeutic doxorubicin." (PMID 39907426, 2025). "Moreover, researchers recently discovered that TCEA3 acts as a tumor promoter in colorectal cancer." (PMID 39907426, 2025).
rhabdomyosarcoma (3 papers, 2020 to 2025). A rare aggressive malignant mesenchymal neoplasm arising from skeletal muscle. "Rhabdomyosarcoma (RMS) is a pediatric cancer derived from the muscle lineage, but the expression or function of TCEA3 in RMS was uncharacterized." (PMID 31988307, 2020).
osteosarcoma (2 papers, 2022 to 2025). A usually aggressive malignant bone-forming mesenchymal neoplasm, predominantly affecting adolescents and young adults. "The four osteosarcoma cell lines generally exhibited higher TCEA3 expression and lower PRKACB, AIM1, and EVI2B compared with the osteoblast cell line (hFOB1.19)." (PMID 36275664, 2022).
adenoma (1 paper, 2021). A neoplasm arising from the epithelium. "TCEA3 was also related to the malignant transformation of adenoma to adenoma with early carcinoma and the development of lymph node metastases in CRC." (PMID 33670246, 2021). "The TCEA3 gene was also related to the malignant transformation of adenoma to adenoma with early carcinoma and development of lymph node metastases in CRC." (PMID 33670246, 2021). "Statistically significant results include 6.20-fold downregulation of SLITRK6 (p = 0.010) in adenomas, and 3.22-fold upregulation of TCEA3 in adenomas with early carcinoma (p = 0.006)." (PMID 33670246, 2021). "We also observed statistically significant 4.58-fold upregulation in adenoma with early carcinoma compared to adenoma for the gene TCEA3 (p ≤ 0.001)." (PMID 33670246, 2021). "Gene TCEA3 showed variable expression in our study, with significant upregulation in adenoma with early carcinoma and CRC without lymph node metastases." (PMID 33670246, 2021).
alopecia (1 paper, 2022). Hair loss usually from the scalp. "In the top 10 down-regulated DEGs, KLK5 (kallikrein related peptidase 5) and TCEA3 (transcription elongation factor A3) were 10 and sixfold lower in alopecia males than normal males, respectively." (PMID 35413801, 2022).
cardiac hypertrophy (1 paper, 2023). "Consider the close link between fatty acid oxidation and mitochondrial ROS during cardiac hypertrophy, We next asked whether reduction in oxidative stress is a mechanism underlying Tcea3-mediated protection of cardiac function." (PMID 37404738, 2023). "Since cardiac hypertrophy is associated with substrate conversion from fatty acids to glucose, we hypothesized that decreased Tcea3 leads to decreased fatty acid oxidation and increased mitochondrial oxidative stress, ultimately leading to further exacerbation of cardiac hypertrophy." (PMID 37404738, 2023). "In this study, we employed a range of bioinformatics tools to identify Tcea3 as a differentially expressed gene, and predicted its involvement in fatty acid oxidation during cardiac hypertrophy." (PMID 37404738, 2023). "We further conduct correlation analysis between Tcea3 and the cardiac hypertrophy markers." (PMID 37404738, 2023).
dilated cardiomyopathy (1 paper, 2023). Cardiomyopathy which is characterized by dilation and contractile dysfunction of the left and right ventricles. "We also detected downregulation of Tcea3 expression in dilated cardiomyopathy tissue from humans, indicating the potential clinical application of Tcea3 as an anti-myocardial remodeling agent, which, however, needs to be further confirmed." (PMID 37404738, 2023).
failure heart (1 paper, 2023). "Box-plot revealing that the expression levels of Tcea3 is significantly different between failure heart, nonfailure heart and sham heart in the GSE36074 dataset." (PMID 37404738, 2023). "To further understand the biological function of Tcea3 in the process of cardiac remodeling, we performed GSEA analysis based on the expression level of Tcea3 to determine the molecular mechanism of Tcea3 affecting the progression of heart failure." (PMID 37404738, 2023).
prostate carcinoma (1 paper, 2020). A carcinoma that arises from epithelial cells of the prostate gland. "Additionally, we show that TCEA3 can initiate apoptosis in cancer cell lines representing cervical, breast, and prostate cancer." (PMID 31988307, 2020). "We found that ectopic expression of TCEA3 also promotes apoptosis in HeLa, MCF7, MDA-231, and PC3 cell lines, representing cervical, breast, and prostate cancer, respectively." (PMID 31988307, 2020).
soft tissue sarcoma (1 paper, 2020). A malignant neoplasm arising from muscle tissue, adipose tissue, blood vessels, fibrous tissue, or other supportive tissues excluding the bones. "This correlation could be seen in a comparison with only soft tissue sarcoma cell lines, but could also be seen in a comparison of all cancer cell lines, suggesting that DNA methylation silencing of TCEA3 is a common mechanism in cancer cells." (PMID 31988307, 2020).
testicular germ cell tumor (1 paper, 2025). A germ cell tumor arising from the testis. "TCGA database analysis showed that up-regulation of TCEA3 expression was negatively correlated with overall survival (OS) and disease-free survival (DFS) in brain lower-grade glioma (LGG) patients (A and B) and OS in testicular germ cell tumors (TGCT)." (PMID 39907426, 2025).
Vertigo (1 paper, 2022). An abnormal sensation of spinning while the body is actually stationary. "The eQTL-based TWAS identified 99 cis-regulated expression genes associated with vertigo, such as RAB3B (PTWAS = 0.017), TMEM132E (PTWAS = 0.002), and TCEA3 (PTWAS = 0.037)." (PMID 36519156, 2022).
tumor (7 papers, 2016 to 2025). "Of note, they all derived from tissues expressing high level TCEA3, suggesting that TCEA3 is likely suppressed during tumor development to block apoptosis." (PMID 34630087, 2021). "It will be important to further characterize the function and regulation of TCEA3 to therapeutically harness this potent tumor suppressor and improve treatment strategies for RMS and other cancers." (PMID 31988307, 2020). "We also asked if TCEA3 was downregulated in broad cancer types and we found that TCEA3 was downregulated in all tumor types analyzed." (PMID 31988307, 2020). "In other words, EB neutralized the tumor stimulatory effect induced by TCEA3 overexpression." (PMID 39907426, 2025). "Further, it is conceivable that inhibitors of USP47 and TCEA3 might be effective agents to enhance various chemotherapeutics-induced pyroptosis and increase the effectiveness of anti-tumor therapies." (PMID 34630087, 2021). "Several genes were similarly down-regulated in all T-LGLL, somewhat less markedly in STAT3-mutated cases, e.g. cluster 2 (149 genes, including key receptors like IL23R and KLRB1) and cluster 8 (46 genes, including tumor suppressors like BEND5 and TCEA3)." (PMID 40721648, 2025). "A mechanistic basis for how TCEA3 promotes apoptosis and functions as a tumor suppressor is not yet understood." (PMID 31988307, 2020).
cancer (6 papers, 2016 to 2024). A tumor composed of atypical neoplastic, often pleomorphic cells that invade other tissues. "It has been also found that TCEA3 was downregulated in a variety of cancers types, and the lower TCEA3 expression is associated shorter overall survival of cancer patients." (PMID 34630087, 2021). "While USP47 knockdown sensitized cancer cells to anti-cancer drugs, its enforced expression increased cellular TCEA3 and chemoresistance, which was markedly attenuated by TCEA3 knockdown." (PMID 34630087, 2021). "As cancer cell populations are heterogeneous, we also examined TCEA3 expression by immunofluorescence to determine if TCEA3 was present in a subpopulation of RMS cells." (PMID 31988307, 2020). "However, we also detected EZH2 binding sites in AT/RT-unique DMRs in DE genes such as NEUROG1 and TCEA3, which are shown to be down-regulated in cancer and are relevant for early development." (PMID 38499326, 2024). "However, it has also been found that enforced expression of TCEA3 inhibited proliferation and induced apoptosis in a number lines of cancer cells, including RMS, HeLa, PC3, MCF7, and MDA-321." (PMID 34630087, 2021). "Thus, our results are consistent with other studies and suggest that there is a shared function of TCEA3 in several cancer types." (PMID 31988307, 2020). "Finally, the expression of TCEA3 in cancer was correlated with lifespan and we saw that patients with higher expression of TCEA3 had a significantly higher five-year survival rate." (PMID 31988307, 2020). "We show that TCEA3 sensitizes RMS cell lines to chemotherapeutic drugs, suggesting that reactivating TCEA3 in cancer cells is an attractive novel therapeutic target for RMS treatment that would specifically initiate apoptosis in cancer cells while sparing normal cells." (PMID 31988307, 2020). "Our finding in this study that USP47 is able to deubiquitinate and stabilize TCEA3 indicates that the reduced expression of USP47 may play a significant role in the reduction of TCEA3 in cancers, and it is of great interesting to further identify the E2 and E3 that ubiquitinate TCEA3 in the future." (PMID 34630087, 2021). "Taken together, the data show that TCEA3 is silenced by DNA methylation and suggests a possible mechanism for how TBX2 represses TCEA3 expression in RMS and additional cancer types." (PMID 31988307, 2020).
cardiovascular diseases (1 paper, 2023). "We predict that the role of Tcea3 in myocardial lipid metabolism may provide new insights into the pathogenesis of cardiovascular diseases in clinical settings." (PMID 37404738, 2023).
heart disease (1 paper, 2023). "However, there is no report on the research of Tcea3 in heart disease." (PMID 37404738, 2023). "Interestingly, to our knowledge, the role of Tcea3 in heart disease has not been reported yet." (PMID 37404738, 2023).
myopathy (1 paper, 2023). A disease of the muscle in which the muscle fibers do not function properly. "Because exercise intolerance and myopathy are often associated with the m.13513G>A variant, we can speculate that upregulation of TCEA3 expression in cells harboring the variant may serve as a compensatory mechanism for defects in muscle functions." (PMID 36975485, 2023).
TCEA3 also shares sentences with these, for which no sentence is quoted: gastric tumor (2 papers); autism (1); bipolar disorder (1); lymphoma (1); renal clear cell carcinoma (1); schizophrenia (1).